MIR1915 (microRNA 1915)
Synonyms: hsa-mir-1915; MIRN1915
Gene: MicroRNA gene on chromosome 10 (21,496,562 to 21,496,641, reverse strand). Ensembl gene ENSG00000222071.
Homologues: Orthologues: chimpanzee MIR1915 (100% identical).